CRP (C-reactive protein)
Diseases named in the same sentence as CRP in open-access papers (continued):
Sharing a sentence is not in itself a finding about the gene and the disease.
periodontitis (continued). "This study provides a comprehensive analysis of key inflammatory biomarkers (CRP, IL-1, IL-6, TNF-α) across all stages and grades of periodontitis, offering detailed insights into both systemic and local inflammatory responses." (PMID 41440349, 2025). "C-reactive protein (CRP), an acute-phase reactant produced primarily in the liver in response to inflammatory cytokines like IL-6, is elevated in both CVD and periodontitis." (PMID 40136726, 2025). "While previous research has largely focused on systemic inflammation markers such as CRP, our study highlights the dual role of inflammation and fibrosis in CKD pathophysiology among periodontitis patients." (PMID 40452929, 2025). "The results showed that PA significantly reduced IL-1β, IL-6, TNF-α, CRP, and LPO levels and increased IL-10 levels in the periodontitis group; moreover, the histological analysis showed reduced inflammatory infiltrate and less fiber degradation." (PMID 40422620, 2025). "Inflammatory mediators, such as C-reactive protein and interleukin-6, play a crucial role in the pathogenesis of CVD in periodontitis patients." (PMID 40283848, 2025). "While our study sheds light on the correlation between CRP and MIP-1α levels in periodontitis and AMI patients, some limitations inherent to cross-sectional studies restrict making predictive statements." (PMID 38433948, 2024). "Periodontitis and HDL-cholesterol were significant predictors of serum NLRP3 while periodontitis and CRP were the significant predictors of salivary NLRP3." (PMID 38954692, 2024). "Treatment of periodontitis effected IL-6, LDL, HDL, TC, TG and SBP with moderate certainty of evidence while the certainty of evidence on CRP, IL-1β, TNF-α, DBP and FMD was low." (PMID 38877442, 2024). "The mechanism of this pathogenic linkage (initiating from periodontitis and leading to AD), is mainly through gram-negative bacteria and viruses which together enhance the pertinent cytokines, especially the ones that are considered to be the acute phase reactants (CRP)." (PMID 38196480, 2024). "A systemic inflammatory-immune response to periodontitis, as indicated by PISA and sites with PPD ≥ 5 mm, was characterized by fluctuations in blood CRP, leukocyte, neutrophil, erythrocyte, uric acid, and CoQ10 levels." (PMID 39797107, 2024). "Extensive research has explored the connections between periodontitis and various blood cell components, including ESR, CRP, IL-6, fibrinogen, Von Willebrand factor, and thrombocytes." (PMID 38595889, 2024). "In conclusion, moderate certainty evidence shows that NSPT has a positive effect on the reduction of IL-6 and SBP in patients with periodontitis, while low certainty evidence shows that NSPT is effective for reduction of CRP." (PMID 38877442, 2024). "Moderate certainty evidence shows that NSPT has a positive effect on the reduction of IL-6 and SBP in patients with periodontitis, while low certainty evidence shows that NSPT is effective for reduction of CRP." (PMID 38877442, 2024). "Patients with periodontitis have higher values of white blood cells, interleukin (IL)-1, IL-6, tumor necrosis factor (TNF)-α and C-reactive protein (CRP)." (PMID 38573898, 2024). "Increased plasma levels of IL-1β, IL-6, TNF-α, CRP, MMP-8, and MMP-9 have been observed in patients with periodontitis." (PMID 38672972, 2024). "Patients with periodontitis show higher levels of pro-inflammatory cytokines such as IL-1, IL-6, TNF, IFN-γ, IL-17, oncostatin M and CRP, and fibrinogen, as well as an increased number of neutrophils compared to the healthy control group." (PMID 38892299, 2024). "Several blood cell components, including erythrocyte sedimentation rate (ESR), C-reactive protein (CRP), interleukin-6 (IL-6), fibrinogen, Von Willebrand factor, and thrombocytes, have been studied in connection with periodontitis." (PMID 38595889, 2024).
periodontitis (continued). "The study concludes that strong correlations exist between CRP, LDH, IL-6 levels, periodontitis, and conventional indices in pregnant females, emphasizing the need for early diagnosis." (PMID 38595889, 2024). "We observed lower adiponectin levels in periodontitis and AMI patients, with considerably higher levels in controls and high levels of MIP-1α and CRP in periodontitis patients and higher levels in AMI patients with periodontitis." (PMID 38433948, 2024). "White blood cell counts, especially neutrophils and C-reactive protein (CRP), are elevated in periodontitis, but the relationship between periodontitis and red blood cell count is inconsistent." (PMID 39797107, 2024). "In this instance, given the substantial reduction in serum ALP 48,53, CRP 48,53, and salivary PCT levels 52, curcumin is considered effective in periodontitis therapy." (PMID 39912085, 2024). "Various data have been obtained on the relationship between body mass index (BMI) and C-reactive protein (CRP) and periodontitis." (PMID 37481511, 2023). "This study aimed to quantify serum C-reactive protein (CRP) values in periodontally healthy people and explore the relationship between serum CRP levels and chronic periodontitis, and the influence of scaling as well as root planing (SRP) on serum CRP levels." (PMID 37568846, 2023). "The researchers found that individuals with severe periodontitis patients exhibited significantly lower serum and saliva levels of NO metabolites and significantly higher LDL, cholesterol, and CRP levels than the control group." (PMID 37711924, 2023). "In this study, we found increased levels of CRP, increased frequencies of CD28−CD57+CD8+ T-cells and a higher prevalence of Pg and Pm in PLWH with severe periodontitis." (PMID 36316604, 2023). "A strong degree of positive correlation is observed within levels of CRP and ORM in several inflammatory conditions such as experimental periodontitis, bacterial infection in neonates, and psoriasis." (PMID 37894947, 2023). "Biochemical markers like CRP and ALP have been used as valuable adjuncts for diagnosing periodontitis." (PMID 37070360, 2023). "Owing to the inflammatory changes in the periodontium, patients with periodontitis may have altered molecular and cellular components in their peripheral blood, and this low-grade systemic inflammation that is fueled by regional inflammatory mediators results in the production of CRP." (PMID 37575815, 2023). "Elevated systemic inflammatory cytokines, such as Interleukin-1β (IL-1β), Interleukin-6 (IL-6), C-Reactive protein (CRP), and Tumor necrosis factor-α (TNF-α), were attributable to periodontitis have been documented by previous studies." (PMID 35162556, 2022). "Third, both periodontitis and CHD have a similar inflammatory pathway leading to higher levels of C-reactive protein (CRP) and other inflammatory markers." (PMID 35877407, 2022). "Periodontitis-induced free radicals and proinflammatory cytokines (IL6, IL17, TNF, CRP) can even activate the hepatocytes and increase CRP production, increasing the systemic inflammatory burden and AGE formation." (PMID 35625570, 2022). "An ELISA was conducted on the plasma of the healthy and periodontitis groups to measure changes in CRIP1 and IFITM1 protein concentrations, and compared with those of the inflammatory markers TNF-α, CRP, and ESR." (PMID 36329504, 2022). "The levels of various APPs in GCF, such as C-reactive protein (CRP), PTX family protein, fibrin, and haptoglobin, are affected by the local periodontitis response." (PMID 34211440, 2021). "A significant correlation between periodontitis and NAFLD was found among those with <1 mg/L serum CRP levels and/or with lower than the median weighted genetic CRP score." (PMID 33918456, 2021).
periodontitis (continued). "Indeed, the augmentation of systemic markers due to periodontitis, such as specific interleukins, fibrinogen, albumin, CRP, matrix metalloproteinase-9 or tumor necrosis factor-α, participate to the vascular endothelial weakening and its dysfunction and, therefore, can promote systemic diseases." (PMID 35096635, 2021). "Human studies have demonstrated that patients suffering from periodontitis exhibit higher concentrations of proinflammatory cytokines, such as tumor necrosis factor-alpha (TNF-α), C-reactive protein (CRP), interleukin-6 (IL-6) and Il-1β." (PMID 33804123, 2021). "Increased serum TREM-1 levels correlated with PGLYRP1, CRP and DAS-28-ESR in RA patients with periodontitis." (PMID 33536478, 2021). "In patients with periodontitis, inflammatory markers (IL-6, IL-10, TNF-α, C-reactive protein, and ALP) in the gingival crevicular fluid are increased and directly correlated with the severity of the disease." (PMID 33430249, 2021). "In comparison to controls subjects, patients with CVD, periodontitis, and periodontitis + CVD had elevated values of hs-CRP (p < 0.001)." (PMID 33810003, 2021). "NSPT produced a significant improvement of the clinical periodontal status of periodontitis patients with chronic hepatitis C, as reflected by the clinical periodontal examination and ELISA assessment of the GCF PTX3 and CRP levels." (PMID 34830557, 2021). "The authors concluded that in the obese rat model, periodontitis increased the systemic LGI thereby upregulating the gene expression for hepatic levels of TNF-α and CRP and for IL-6 and CRP in the adipose tissue." (PMID 32486269, 2020). "Additionally, the severity of periodontitis may have a direct impact on the levels of CRP." (PMID 32994872, 2020). "Compared to healty controls, patients with periodontitis, CDH and a combination of periodontitis+CHD presented a higher values of hs-CRP (p < 0.001)." (PMID 32015361, 2020). "Thus, the presence of periodontitis may increase CRP levels." (PMID 33424972, 2020). "Through a univariate regression analysis, c-reactive protein (CRP) and CHD (both p < 0.001) and periodontitis (p = 0.029) were statistically correlated with ET-1 in serum." (PMID 32015361, 2020). "This study found that the presence of periodontitis in CHD patients contributed to increased levels of serum and salivary MAA and CRP levels." (PMID 31805680, 2019). "Experimental periodontitis in obese rats resulted with an increased gene expression of TNF-alpha and CRP in liver and increased levels of IL-6 and CRP in adipose tissue." (PMID 29936690, 2019). "Increased levels of pro-inflammatory mediators such as interleukin-6 (IL-6), C-reactive protein (CRP) and matrix metalloproteinase 9 (MMP-9) have been observed among people with periodontitis." (PMID 30873290, 2019). "Higher levels of serum IL-6, C-reactive protein (CRP), TNF-α and IL-1β have been reported among periodontitis patients in several studies." (PMID 29980169, 2018). "Of the 20 cytokines examined, CRP was significantly (one-way ANOVA, P < 0.05) higher in the GCF of the periodontitis group while IL-8 was significantly (one-way ANOVA, P < 0.01) higher in the GCF of the healthy group." (PMID 29163429, 2017). "A pilot study comparing CRP and SAA levels found that both were elevated in periodontitis patients and SAA, along with CRP, are valuable markers to identify inflammatory conditions in patients." (PMID 28326084, 2017). "In both periodontitis patient groups, BOP showed much better positive correlation with the levels of CRP compared to PD." (PMID 26346216, 2015). "Pearson correlation coefficients between serum CRP, MCP-1, eotaxin, and BMI in periodontitis (PD) and in periodontally healthy (PH) subjects." (PMID 26241961, 2015). "In summary, we identify higher serum levels of CRP, eotaxin and MCP-1 in subjects with periodontitis." (PMID 26241961, 2015).
periodontitis (continued). "This, together with our finding that both CRP and MCP-1 correlates with BMI points towards an increased systemic load of inflammatory mediators in patients with periodontitis and high BMI." (PMID 26241961, 2015). "This, together with our finding that both CRP and MCP-1 correlates with BMI points towards an increased systemic inflammatory load in patients with periodontitis and high BMI." (PMID 26241961, 2015). "Substances such as C-reactive protein (CRP), aspartate amino transferase (AST), tumor necrosis factor-alpha (TNF-α), and prostaglandin (PG) E2 have been extensively assayed for periodontitis leading to other subclinical infection." (PMID 24692844, 2014). "Low grade inflammation, reflected as increased levels of C-reactive protein (CRP) and other inflammatory markers, is considered as a biologically plausible link between periodontitis and cardiovascular diseases." (PMID 24386401, 2013). "Other studied parameters, including PTH, TSH, T3, T4, cortisol, human-grown hormone, platelets count, total proteins, CRP, and fecal calprotectin, were all nonsignificantly different and without correlation depending on the presence of periodontitis." (PMID 40559437, 2025). "System inflammation due to periodontitis results in elevated TNF-α, CRP AND IL-6 in women with GDM." (PMID 41394354, 2025). "In non-human primates, ligature-induced periodontitis elevated acute-phase proteins, such as CRP and fibrinogen, which normalized after treatment." (PMID 40136726, 2025). "In a clinic-based cross-sectional study, participants with periodontitis had greater odds of altered CRP (≥3 mg/L) than those without the disease (OR = 3.27; 95% CI 1.42–7.52)." (PMID 41301163, 2025). "Immune-inflammatory agents, namely CRP, TNF-α, CXCL10, IL-6, IL-18, sVCAM-1, sICAM-1, IP-10 and MCP-1, have been found in high concentrations in the circulating blood of pregnant individuals diagnosed with preeclampsia who also have periodontitis." (PMID 41394354, 2025). "These curves were stratified by the presence or absence of embedded or impacted teeth, periodontitis, CRP levels, and gender." (PMID 40076898, 2025). "In the samples taken at the start of the current study, the CRP level was observed to be significantly higher in the patients with periodontitis compared to those without periodontitis." (PMID 38195732, 2024). "Compared with the participants without periodontitis and possessing CRP levels of ≤ 0.5 mg/dL, those with periodontitis (hazard ratio [HR], 1.38) or CRP levels of > 0.5 mg/dL (HR 1.23) had higher HRs." (PMID 39453923, 2024). "A non-significant decreasing trend of CRP values at 6 months after treatment for periodontitis patients with comorbid CVD was reported." (PMID 38667035, 2024). "The meta-analysis revealed significant reductions in markers such as high-sensitivity C-reactive protein (his-CRP), interleukin (IL)-6, and plasma glucose, along with improvements in Flow-Mediated Dilation (FMD) and diastolic blood pressure after periodontitis treatment." (PMID 39607148, 2024). "For instance, although we observed elevated CRP levels in both AMI and periodontitis patients, whether high values are present post-MI or during the time leading to cardiac ischemia remains debatable." (PMID 38433948, 2024). "A recent meta-analysis that focused on CRP values alone concluded that treatment of periodontitis reduces serum CRP levels (up to 6 months follow-up), and no treatment effect was observed at 12 months or beyond." (PMID 38877442, 2024). "In patients with both periodontitis and concurrent CVD, subgingival mechanical instrumentation can mitigate systemic inflammation, as evidenced by reduced levels of proinflammatory markers such as C-reactive protein, calprotectin, and white blood cell counts." (PMID 38667035, 2024).
periodontitis (continued). "Given these considerations, this study aimed to assess and establish links between periodontal health and blood levels of IL-6, LDH, and CRP among second-trimester pregnant women, regardless of their chronic periodontitis status." (PMID 38595889, 2024). "Physical training resulted in a reduced levels of IL-1β, IL-6, TNF-α C-reactive protein and LPO and an increase in the levels of IL-10 in rats with periodontitis (p<0.05); a reduction in the inflammatory infiltrate and decreased fiber degradation was identified in histological analysis." (PMID 38843156, 2024). "Compared with the participants without periodontitis and CRP levels of ≤ 0.5 mg/dL, those with both periodontitis and CRP levels of > 0.5 mg/dL demonstrated the highest HR of 2.01." (PMID 39453923, 2024). "In our carefully selected population, CRP was slightly higher than reference values but periodontitis in the clinical setting had no influence on inflammatory blood values." (PMID 38804312, 2024). "The objective of this study was to compare the periodontal health and blood levels of IL-6, LDH, and CRP in pregnant women with and without chronic periodontitis." (PMID 38595889, 2024). "Studies have shown a higher neutrophil–lymphocyte ratio (NLR), a lower lymphocyte-monocyte ratio (LMR), increased levels of proinflammatory cytokines such as interleukin 17 (IL‐17), C-reactive protein (CRP), and fibrinogen in patients with periodontitis compared to healthy controls." (PMID 37535199, 2023). "A later study conducted in 2018 revealed the positive impact of nonsurgical periodontal therapy in reducing plasma CRP levels in pregnant women with periodontitis." (PMID 37511934, 2023). "The results of the current study showed that the CAD with moderate–severe periodontitis group presented a higher level of IL-6 and CRP in comparison with the mild periodontitis group; however, our results were not statistically significant." (PMID 37239434, 2023). "This meta-analysis showed that in a population of non-HIV participants with periodontitis, a high inflammatory load was reflected by higher levels of CRP." (PMID 36316604, 2023). "Despite the fact that numerous studies have shown an increase in CRP levels in patients with periodontitis, neither of the included studies showed significant effects on CRP." (PMID 36986267, 2023). "In line with previous studies, the results of the present study showed that the EP group had significantly higher serum levels of IL-6, CRP, MMP-8, and ALP and lower levels of IL-10 than the control group confirming that the experimental model used was able to induce experimental periodontitis." (PMID 38033572, 2023). "Although the IL-6 and CRP levels were not significantly different between the two groups, IL-6 levels affected CRP levels in periodontitis patients with CAD." (PMID 37239434, 2023). "Contrary to our findings, a previous study reported a lack of correlation between blood and the GCF levels of CRP in periodontitis subjects." (PMID 38138192, 2023). "Therefore, the aim of the study was to explore the correlation between the markers of systemic and periodontal inflammation as assessed by CRP and the PSGS in participants with periodontitis." (PMID 37575815, 2023). "The objective of this study is to assess whether the interaction of baseline serum levels of TNF-α, hs-CRP, ICAM-1, VCAM-1, and adiponectin leads to periodontitis." (PMID 37371602, 2023). "Because of the chronic nature of the disease, elevated CRP levels are consistently observed in male and non-pregnant subjects diagnosed with periodontitis." (PMID 37511934, 2023). "Mean C-reactive protein levels [CRP, 1.6 mg/L versus 0.8 mg/L, p = 0.020] and percentages of senescent CD28-CD57 + CD8 + T-cells in peripheral blood [16.5 versus 8.9, p = 0.035] were higher with severe periodontitis." (PMID 36316604, 2023).